STAT3 (signal transducer and activator of transcription 3)
Diseases named in the same sentence as STAT3 in open-access papers (continued):
Sharing a sentence is not in itself a finding about the gene and the disease.
tumor (continued). "Moreover, STAT3 is able to transmit signals from the cell surface to the nucleus in the activation of growth and cytokines factors, which could improve the survival rate of tumor cells." (PMID 34165442, 2021). "IL-6 plays a significant role in inducing tumor growth as it interacts with the receptor, JAK, to induce STAT-3 activation." (PMID 34307156, 2021). "Taken together, these data demonstrate that MAFF is a positive regulator of tumor cell invasion and metastasis by activating IL11/STAT3 pathways when binding to BACH1, especially under hypoxic conditions." (PMID 34262028, 2021). "STAT3 has also been found to be a Src-dependent mediator of EGFR-stimulated growth of HNSCC in vitro and decreased apoptosis and increased tumour growth in vivo." (PMID 34298667, 2021). "Meanwhile, IHC staining was performed to confirm that the phosphorylation levels of MEK1/2, ERK1/2, JAK2, STAT3, PI3K, and Akt in tumor tissues of mice inoculated with A549, BxPC-3, and SKOV3 cells, respectively." (PMID 34642304, 2021). "Herein, we provide the first evidence that ANXA1 is a positive regulator of tumor growth and metastasis in PTC, complementing its biological function via influencing the dynamic properties of EMT and regulating IL-6/JAK2/STAT3 signaling network." (PMID 33531975, 2021). "It is apparent STAT3 is a key molecular driver of CAF function and dictates the crosstalk between cells of the TME to foster tumor development and metastatic spread." (PMID 34858425, 2021). "Numerous tumor-related genes, such as HMGA2, RB1CC1/FIP200, SRCIN1, STAT3, and PTEN, are targeted by miR-20a." (PMID 33504017, 2021). "The M2 phenotype stimulates tumor initiation, progression, and metastasis by various mechanisms involving TLR4/STAT3, TLR4/TRIF/NF-κB, Wnt/β-catenin, and many other pathways." (PMID 34696292, 2021). "The aim of this study was to investigate the irradiation effect on IFNγ-mediated STAT1 and STAT3 phosphorylation and genes expression such as PD-L1 and anti-apoptosis genes in EGFR-positive tumor cells to augment CD8+ T cells cytotoxicity against NSCLC." (PMID 34685495, 2021). "Many studies show that GBM is characterized by an immunosuppressive microenvironment due to a rise of factors released by tumor cells such as programmed cell death protein-1 (PD-1), indolamine 2, 3dioxygenase (IDO), STAT3 and FASL." (PMID 34948224, 2021). "Mechanistically, we find that TR35 exerts anti-tumor effects by activating p-JNK/MAPK signaling and suppressing STAT3 signaling (including its downstream molecules such as c-Myc and Bcl-XL)." (PMID 34760885, 2021). "Inhibition of STAT3, Akt, and ERK signaling pathway, which play pivotal roles in tumor cell proliferation, invasion, and migration, had also been observed." (PMID 33436830, 2021). "Although STAT3 and STAT5 are related to tumor immunosuppression, other members (such as STAT1) can mediate antitumor immunity, which is in contrast to the effects of STAT3 and STAT5a/b." (PMID 34943817, 2021). "We observed a substantial reduction in the phosphorylation of STAT3, JAK1, and JAK2 in the tumor tissues of mice treated with 100 mg/kg of Tris DBA." (PMID 34771643, 2021). "The STAT3-targeted inhibitor Stattic suppressed CCL16 expression in vitro and restrained tumor progression in vivo." (PMID 33500726, 2021). "Meanwhile, genetic ablation of STAT3 in CD8 T-cells enhances their infiltration into tumors, promotes their proliferation, and results in increased cytotoxic T-cell activity and tumor growth inhibition." (PMID 34944848, 2021). "Both cancer cells and in vivo tumor xenografts showed that the combined inhibition of PI3K/AKT/mTOR and STAT3 activity enhanced the inhibitory effect of BEZ235 on the proliferation of PTEN-deficient cancer cells." (PMID 33431808, 2021). "Cross communication between the STAT3 and S1P-SphK-S1PR pathways has recently been discovered to play an important part in inflammation-induced carcinogenesis and tumor growth in the gut." (PMID 34943797, 2021).
tumor (continued). "In GBM, EVs have been found to carry well-known tumor propagating factors such as EGFRvIII, SOX-2 and activators of the PI3K/Akt, PTEN, Erk and STAT3 pathways." (PMID 34337348, 2021). "STAT3 phosphorylation (STAT3 activation) and increased expression of interleukin-10 (IL-10) were detected in 53.1% and 78.1% of PCNSL tumor samples, respectively." (PMID 33996566, 2021). "IL-6 activates the signal transducer and activator of transcription-3 (STAT3) signaling pathway which in turn, acts to promote tumor growth and anti-tumoral immunity." (PMID 32797354, 2021). "Here, we demonstrate that MAFF, which is induced by HIF-1 under hypoxia, binds with BACH1 and promotes tumor invasion and metastasis by transcriptionally activating IL11 and promoting STAT3 pathways." (PMID 34262028, 2021). "The HGF-MET axis orchestrates cell morphology and wound healing in a physiological state, but in cancer, it regulates crucial pathways for tumor growth and metastasis through Ras-MAPK, PI3K, FAK-Src, and STAT3 signaling." (PMID 34037097, 2021). "We demonstrated that IR elicited A549 cell apoptosis and augmented PBMCs-mediated tumor cell death through prohibiting IFNγ-mediated phosphorylation of STAT1 and STAT3 and gene expression of PD-L1 and MCL1." (PMID 34685495, 2021). "Stattic, a Stat3 inhibitor, completely abolishes the promoting effects of LRG1 on tumour cell activation." (PMID 34208965, 2021). "Considering this, miR-142-3p mimic led to a significant inhibition of STAT3 and SOCS5 in tumor tissues." (PMID 33987190, 2021). "Further studies revealed that inhibiting STAT3 enhanced the inhibitive effect of FAD on HCC cells, whereas overexpressing PTTG1 attenuated the anti-tumor effect of FAD." (PMID 34025420, 2021). "Next, we investigated the mechanism by which STAT3 and p‐STAT3 are upregulated in ADSCs‐CRC and the potential influence of tumor cells." (PMID 33999512, 2021). "Consistent upregulation of the ALKBH5-HOXA10 loop promoted EOC tumor growth and resistance to cisplatin by activating the JAK2/STAT3 signaling pathway in the m6A-dependent manner." (PMID 34496932, 2021). "Blockade of IL-6 with tocilizumab and STAT3 knockdown attenuated CD44+ sphere formation and tumor growth of patient-derived HCC as well as breast xenografts." (PMID 34235155, 2021). "Conditional knockouts for STAT3 and STAT5A/B allowed to uncover the effects of STAT3 and STAT5 in T-cell differentiation and memory, dendritic cell function, and NK-cell tumor surveillance." (PMID 34073410, 2021). "Surgical procedure-induced overexpression of IL-11 promoted tumor cell growth and recurrence of HCC via activating STAT3 signaling, while blocking IL-11/STAT3 signaling dampened HCC recurrence after surgical resection." (PMID 35002979, 2021). "Therefore, by inhibiting STAT3, such anti-tumor immune response could be alleviated." (PMID 34440220, 2021). "The overexpression of CD36 requires STAT3 and STAT5 signalling activation, both of which are triggered by tumour-released G-CSF and GM-CSF." (PMID 34685679, 2021). "Thus, targeting STAT3 may improve tumor progression and anticancer response." (PMID 34900688, 2021). "In mice fed a high-fat diet, metformin reduced the activity of the STAT3-ERK-vimentin and fibronectin-integrin signaling pathways, with the outcome of blocking cancer cell vascular invasion and anaplasia and delaying tumor progression." (PMID 34884872, 2021). "The suppressing ability of caffeic acid and its derivative CADPE on the tumor angiogenesis was studied and the result indicates that each compound prevents VEGF expression by blocking STAT3 phosphorylation." (PMID 35052553, 2021).
tumor (continued). "Based on these results and the robust expression of both STAT3 and Ref-1 in MPNST cells and patient samples, we treated the tumour cells with small-molecule inhibitors of Ref-1 or STAT3 signalling." (PMID 33658640, 2021). "A tumour engages in crosstalk with its microenvironment (TME) which can be influenced by both Ref‐1 and STAT3 signalling pathways." (PMID 33274592, 2021). "In gefitinib-resistant NSCLC cells, inhibition of STAT3 reduces PDL1 expression, and enhances the efficacy of anti-PD1/PDL1 immunotherapies in NSCLC tumor-bearing mice." (PMID 34944848, 2021). "Previous tumor bulk analysis identified a related AP-1 family member FOSL2, together with CEBPB, STAT3, and TAZ, as important regulators of the MES GBM subtype." (PMID 34399888, 2021). "Our results revealed that fraxetin enhanced the anti-tumor efficacy of gemcitabine and suppressed oncogenesis and the development of PDA by antagonizing STAT3 activation." (PMID 34320467, 2021). "The activation level of STAT3 modulates DNMT/OCT4, which confers tumor recurrence and prognosis in patients with HCC." (PMID 34948424, 2021). "IL-17, in turn, promoted tumor angiogenesis by inducing angiogenic factors, such as VEGF and PGE2, and activated oncogenic STAT3 signaling, which was essential for the expression of pro-survival and pro-angiogenic genes." (PMID 33418929, 2021). "The network consists of a system of ordinary differential equations (ODEs) involving eight variables: concentrations of STAT1, STAT3, Bcl-2, BAX, IFN-β, JAK2 and DDP and tumour volume." (PMID 34631119, 2021). "Next, the cell permeability of PS-acet.-STAT3 was examined and visualized in CRC patient primary tumor spheres." (PMID 33491667, 2021). "We further analyzed the phosphorylation status of STAT3, JAK1, and JAK2 proteins in the tumor tissues of the xenograft MM mouse model." (PMID 34771643, 2021). "Consistent with the in vitro experiments, in nude mice exnografted with MGC 803 cells, galangin inhibited tumor growth and reversed the abnormally expressed proteins, such as p-JAK2, p-STAT3, Bcl-2, cleaved caspase-3, cleaved PARP, and Ki67." (PMID 33981228, 2021). "In particular, AZD1480 potently inhibited both Stat5 and Stat3 in preclinical models of PC, resulting in reduced PC cell viability and CRPC tumor growth after androgen deprivation conducted by surgical castration." (PMID 34680353, 2021). "Activation of STAT3 induces upregulation of p47phox and gp91, which in turn increases the production of reactive oxygen species by MDSC, as shown in subcutaneous tumor models in mice." (PMID 33917501, 2021). "As a matter of fact, the constitutive activation of STAT3 can be propagated through IL10, IL-8, and VEGF, from tumor to immune cells, which in turn leads to immune suppression." (PMID 34072037, 2021). "m6A sequencing reveals that loss of METTL3 impairs the YTHDF1-mediated translation of SPRED2, which enhances the activation of NF-kB and STAT3 through the ERK pathway, leading to increased tumour growth and metastasis." (PMID 33654093, 2021). "In NSCLC, it was described as a tumor suppressor acting on insulin growth factor (IGF)-1R53, being involved in tumor growth and metastasis through STAT3 and Neuropilin 1 downregulation." (PMID 33451052, 2021). "IL11 enhances tumor cell proliferation, migration, EMT, and invasion of NSCLC cells via activation of STAT3, while depletion of IL11 significantly impairs the growth of NSCLC xenografts in mice and improves survival." (PMID 34944848, 2021). "Collectively, our work identifies an inflammation/immune-associated cellular, molecular and clinical network involving TANs, TAMs and STAT3 signaling in ICC cells, which controls the tumor progression and patient outcome." (PMID 33692217, 2021). "We now concentrated on the molecular endowments of STAT3-controlled treatment resistance and uncovered that CRT-resistant tumor cells are equipped with autonomous NOTCH signaling activity." (PMID 33530306, 2021).
tumor (continued). "The results indicated a significant reduction of STAT3, SP1, and SOCS5 mRNA expression in the splenocytes of CT-26 tumor-bearing mice treated with TEXomiR compared to both the TEX and PBS groups (P < 0.01)." (PMID 33987190, 2021). "STAT3/LINC00671/LDHA axis regulates glycolysis, tumor growth, and lung metastasis of PTC both in vitro and in vivo." (PMID 34404767, 2021). "Furthermore, transient PARPi treatment upregulates STAT3 activation in mouse and human immune cells, leading to enhanced production of immunosuppressive cytokines and reduced expression of immuno-stimulating factors required for T cell-mediated killing of tumor cells." (PMID 34956861, 2021). "Another subset of STAT3-activated B cells found in human prostate, non-small cell lung, and ovarian cancers, CD5+ B cells promote tumor progression upon IL-6 activation." (PMID 34164398, 2021). "Consistently, the protein levels of TRIM44, p-STAT3, BCL2, MMP9, HIF-1α and PIM1 were all decreased in SPATS2 knockdown tumor tissues, which underpinned the contribution of SPATS2-TRIM44-p-STAT3 axis to tumorigenic events in HCC." (PMID 33391405, 2021). "Collectively, these findings suggest that SH003 and DTX inhibit tumor growth by promoting apoptosis and inhibiting the expression of p-EGFR (Y1068) and p-STAT3 (Y705)." (PMID 34445110, 2021). "SUMO-1-modified CPAP enhances the transcriptional activity of NF-κB in HCC cells; overexpressed CPAP directly interacts with STAT3 to enhance IL-6-mediated STAT3 activation and promote HCC tumor growth and metastasis." (PMID 34686650, 2021). "Reports across a variety of tumor and endothelial cell types have suggested members of the JAK family, SRC and the intrinsic kinase activity of VEGFR-2 as VEGF-induced activators of STAT3." (PMID 34542605, 2021). "Herein, we provide the first evidence that Niclocide is an inhibitor of tumor growth and metastasis in PTC, complementing its biological function via influencing the dynamic properties of regulating JAK2/STAT3 signaling network." (PMID 34404767, 2021). "Here we report that nicotine enhances ESCC cancer malignancy and tumor-initiating capacity by interacting with cholinergic receptor nicotinic alpha 7 subunit (CHRNA7) and subsequently activating the JAK2/STAT3 signaling pathway." (PMID 33603170, 2021). "Columbamine significantly decreases tumor volumes in HCT116 or SMMC7721 xenograft mouse model, as well as induces cell apoptosis and G2/M phase arrest via Wnt/β-catenin, MAPK, CDK6, STAT3 signaling pathways in in vitro models." (PMID 35046810, 2021). "Two major signals from our study, STAT3 and TRAF2, are involved in miR-671-5p-regulated tumor migration." (PMID 35052701, 2021). "The immunohistochemical evaluation of p-STAT3 in 108 CRC cases demonstrated cytoplasmic and nuclear expression, positive correlation of pSTAT3 expression, with the depth of the tumor invasion, Dukes, TNM stage, and reduced overall survival." (PMID 34440220, 2021). "STAT3, like STAT5 and STAT6, affects the tumor microenvironment (TME), boosting immunosuppressive TMEs and decreasing anti-tumor immunity." (PMID 34952583, 2021). "The effects of the JAK/STAT pathway and the persistent activation of STAT3 and STAT5 during the process of tumor cell proliferation, cycling, and invasion have made it a favorite treatment target." (PMID 33671013, 2021). "In the tumor microenvironment, IL‐6/JAK/STAT3 signaling acts to drive the proliferation, survival, invasiveness, and metastasis of tumor cells." (PMID 34026434, 2021).
tumor (continued). "The phosphorylated STAT3 (p-STAT3) protein may then be transported to the nucleus where it attaches to DNA and stimulates the transcription of numerous genes that control critical cell activity, including cell survival, proliferation, new vessel formation and tumour evasion." (PMID 33809542, 2021). "By conjugating a PS DNA oligonucleotide to a synthetic acetylated STAT3 (K685), MYC, or Gp130 peptide, we show PS modification can also facilitate efficient penetration of peptide into tumor cells and tumor tissues in vivo." (PMID 33491667, 2021). "It has been evidenced from cell lines experiments conducted on SKBR3 and MDA-MB-453, HER2 positive cell lines that apigenin successfully reduces the expression of STAT3, STAT5 and JAK2 thus preventing tumor proliferation and growth." (PMID 33794890, 2021). "Tumor-Educated Myeloid Cells (TEMC), which are abundantly found in the TME, can be targeted by nanoparticles harboring short hairpin RNA (shRNA) against STAT3 and C/EBPβ." (PMID 34065010, 2021). "In a STAT3/ERK1,2-dependent manner, IL-6 promoted proliferation and survival of tumor cells, protected them from drug-induced apoptosis in vitro and stimulated tumor growth in vivo." (PMID 33287630, 2021). "Mechanistically, afatinib and dacomitinib induce STAT3 activation via promoting autocrine IL6 secretion in cancer cells, which potentiates drug resistance via a paracrine loop between fibroblasts and tumor cells." (PMID 34944848, 2021). "In the tumor microenvironment, IL-6/JAK/STAT3 signaling pathway plays a pivotal role in regulating the growth, survival, invasiveness, metastasis, and development of many cancers." (PMID 35155571, 2021). "Earlier research indicated that the STAT3 protein binds to the VEGFA promoter in vivo and found that constitutive STAT3 activity upregulates VEGFA expression and tumor angiogenesis." (PMID 34059068, 2021). "Mechanically, EVs released from NSCLC cells can induce anaplastic lymphoma kinase inhibitors-resistant or Ceritinib-resistant phenotype upon target tumor cells via stimulating AKT, STAT3 and ERK pathways." (PMID 35059436, 2021). "Conversely, leptin knock-down impairs NSCLC tumor cell proliferation and induces apoptosis by inhibiting JAK/STAT3 signaling." (PMID 34944848, 2021). "In the tumor microenvironment, IL-6/JAK STAT3 signaling contributes to proliferation, invasiveness, and metastasis of tumor cells and strongly inhibits the antitumor immune response." (PMID 33912584, 2021). "PDGFRs, VEGFRs, and FGFRs signal via the SRC kinase and regulate STAT3, AKT, ERK, MAPK, or JNK-mediated proliferative and migratory pathways in tumor cells." (PMID 34650051, 2021). "It has been reported that different cell types in the tumor niches produce IL-6, and the IL-6/JAK/STAT3 pathway is aberrantly hyperactivated in many cancers, leading to the increased tumor-cell growth and progression, survival, and metastasis." (PMID 33461943, 2021). "In tumor tissues from galangin treated mice, the ratios of p-JAK2/JAK2 and p-STAT3/STAT3, as well as the protein expressions of Bcl-2, caspase-3 and Ki67 were all reduced remarkably (p < 0.01 or p < 0.001)." (PMID 33981228, 2021). "IL-6 binds with IL-6R to induce the activation of STAT3, and activated STAT3 binds to the promoter region of the VEGF gene to increase transcription, promoting the formation of tumor angiogenesis." (PMID 34976809, 2021). "The PI3K/AKT, STAT3, and PDCD4/TNF-α signaling networks, regulated by the microRNA (miR)-21, are critical for inflammatory regulation, tumor suppressor modulation, and oncogenic activation." (PMID 34771727, 2021). "PKM2 overexpression in DLD1 cells upregulated STAT3 gene transcription and activated downstream snail-2 and β1-integrin-FAK signaling to induce tumor migration." (PMID 34887764, 2021).